GLP1R (glucagon like peptide 1 receptor)
Diseases named in the same sentence as GLP1R in open-access papers (continued):
Sharing a sentence is not in itself a finding about the gene and the disease.
diabetes (continued). "Both glucagon-like peptide-1 receptor agonists (GLP-1RA) and sodium-glucose cotransporter-2 (SGLT-2) inhibitors can reduce CV risk in patients with T2D, and both are recommended by the American Diabetes Association to reduce the risk of major cardiovascular events (MACE)." (PMID 34641876, 2021). "In a diet-induced mouse model of diabetes supplemented with streptozotocin (STZ) administration, chronic GLP-1R stimulation partially rescued the decrease in beta cell mass, confirming the role of cAMP in morphological adaptation, even in the setting of decompensated diabetes." (PMID 34359828, 2021). "Besides preventing diabetes-induced neurodegeneration, topical administration of semaglutide inhibits the disruption of the blood-retinal barrier and the subsequent vascular leakage, thus confirming the dual effect of GLP-1R agonists." (PMID 34440130, 2021). "In the light of theranostics/radiotheranostics and prospective of personalized medicine in diabetes and oncology, this review presents prior and current advances in the development of radiolabeled imaging and radiotherapeutic exendin-based agents targeting glucagon-like peptide-1 receptor." (PMID 31903131, 2020). "Whether reduced GLP-1r in the stomach is a result of diabetes?" (PMID 31292518, 2019). "Exendin-4, an agonistic polypeptide for human GLP-1R derived from the venom of the Gila monster lizard, has also been shown to enhance lysosomal function in β-cells, improve autophagosome clearance and protect against islet injury in a rat model of tacrolimus-induced diabetes." (PMID 31156426, 2019). "Thus, GLP-1R agonists has been considered as potential agents against diabetes." (PMID 30301245, 2018). "Furthermore, when administered in a time-specific manner, chronic d-allulose corrects arrhythmic overeating, obesity and diabetes, suggesting that chronotherapeutic modulation of vagal afferent GLP-1R signaling may aid in treating metabolic disorders." (PMID 29317623, 2018). "Moreover, downregulation of GLP-1R level is also found in the glomerular endothelial cells of diabetic mice, which may be due to increased GLP-1R degradation resulted from diabetes-induced PKCβ2 activation." (PMID 28145471, 2017). "In addition, some diabetes drugs targeting the glucagon-like peptide-1 receptor, such as metformin and thiazolidinediones, may promote neuronal survival by affecting brain metabolism, neuroinflammation, and regeneration." (PMID 29099813, 2017). "GLP-1R agonists are in clinical use for the treatment of diabetes and several studies indicate that they may be useful in the treatment of ischemic stroke, but the neuroprotective efficiency of orally administered low molecular weight agonists has not been reported." (PMID 26863436, 2016). "However, the gene expression and functionality of CNS GLP-1 receptor (GLP-1R) remain largely unknown in diabetes after RYGB surgery." (PMID 27648071, 2016). "On the other hand, mitochondrial oxygen consumption was impaired in the diabetes related mouse model.Our previous observation also indicates that stimulation of GLP-1R could increase mitochondrial oxygen consumption in myoblasts exposed to hypoxia/reoxygenation." (PMID 26245924, 2015). "Semaglutide, a long-acting glucagon-like peptide-1 receptor agonist (GLP-1RA), has transformed obesity and diabetes management." (PMID 42193128, 2026). "Glucagon-like peptide-1 receptor agonists (GLP-1RAs) and newer dual-incretin therapies have become central to the treatment of diabetes mellitus and obesity, with benefits extending beyond glycemic control." (PMID 42201157, 2026). "Glucagon-like peptide-1 receptor agonists (GLP-1RAs), approved for diabetes and obesity, have shown promise in modulating reward-related brain pathways, suggesting potential benefits in the management of AUD." (PMID 41508124, 2026). "Background and objective Glucagon-like peptide-1 receptor agonists (GLP-1 RAs), especially semaglutide, are commonly used to treat obesity and diabetes." (PMID 41669596, 2026).
diabetes (continued). "Recently, more novel treatments known as glucagon-like peptide-1 receptor agonists (GLP-1RAs) and their analogues (originally developed to treat diabetes) are increasingly used in treatment plans." (PMID 40860963, 2025). "Furthermore, with the advent of new treatments such as Glucagon-Like Peptide-1 receptor agonists, which have demonstrated cardioprotective and metabolic benefits in population with diabetes, it remains unclear how these therapies may influence outcomes in SPKT versus DDKT recipients." (PMID 41536839, 2025). "GPCRs, including the GLP1 receptor (GLP1R), serve as essential mediators of various cellular processes and represent important therapeutic targets for a range of diseases, including diabetes." (PMID 40149584, 2025). "Glucagon-like peptide-1 receptor agonists (GLP-1 RAs), primarily used for glycemic control and weight management in diabetes and obesity, have shown potential in cancer prevention through various mechanisms." (PMID 40364115, 2025). "Moreover, studies have shown that GLP-1R agonists may downregulate NF-κB activation in podocytes, glomerular endothelial cells, monocyte/macrophages, and mesangial cells, thereby inhibiting tge inflammatory response in diabetes models." (PMID 41280890, 2025). "The actions of GLP-1 on insulin and glucagon secretion inspired the development of several GLP-1 receptor (GLP-1R) agonists that have revolutionized treatment for obesity and diabetes." (PMID 41178720, 2025). "Background/Objectives: Glucagon-like peptide-1 receptor agonists (GLP-1RAs) and sodium-glucose cotransporter-2 inhibitors (SGLT-2Is) have significantly improved the management of diabetes mellitus (DM)." (PMID 40648992, 2025). "Pathological states such as diabetes and vascular injury can suppress GLP1R expression, potentially compromising the efficacy of GLP-1 receptor agonists." (PMID 41011133, 2025). "The study investigated the inhibitory potential of 27 compounds from M. indica leaves against three diabetes-related enzymes: GSK-3β, DPP-IV, and GLP-1R." (PMID 41465578, 2025). "Clinical trials have shown that the new therapies of sodium glucose cotransporter-2 (SGLT-2) inhibitors and glucagon like peptide-1 receptor agonists (GLP-1RA) to improve cardiorenal outcomes and their actions extend to include older people with diabetes." (PMID 39852391, 2025). "Multi-target peptide therapeutics targeting glucagon receptor (GCGR), glucagon-like peptide-1 receptor (GLP1R), and glucose-dependent insulinotropic polypeptide receptor (GIPR) represent a promising approach for treating diabetes and obesity." (PMID 41333850, 2025). "This crucial function of GLP-1R has led to the successful development and commercialization of GLP-1 receptor agonists (GLP-1RAs) as effective treatments for diabetes." (PMID 40076236, 2025). "There is growing interest in the relationship between Alzheimer’s disease (AD) and diabetes mellitus (DM), and the glucagon-like peptide-1 receptor (GLP-1R) may be an important link between these two diseases." (PMID 40778306, 2025). "Although TZP, as the first GLP‐1R/GIPR dual agonist, has been approved by the FDA for the treatment of diabetes, its anti‐tumor mechanisms and the specific relationship with receptors activation to downstream molecules still require further exploration." (PMID 40125821, 2025). "The therapeutic potential of glucagon-like peptide-1 receptor agonists (GLP1RAs), such as semaglutide, and dual GIP receptor (GIPR)/GLP1RAs, like tirzepatide, extends beyond metabolic diseases like diabetes and obesity." (PMID 40931165, 2025). "Studies have shown that Black patients are less likely to receive newer diabetes medications, including SGLT-2 inhibitors (SGLT-2is) and glucagon-like peptide-1 receptor agonists (GLP-1 RAs), than White patients." (PMID 38592214, 2024).
diabetes (continued). "In summary, the collective evidence from various studies, including those exploring dual agonists (GLP-1R/GIPR) and tri-agonists (GLP-1R/GIPR/GCGR), demonstrates unprecedented improvements in diabetes and body weight compared to GLP-1RA treatment alone." (PMID 39145614, 2024). "Glucagon-like peptide-1 receptor agonists (GLP-1RA), commonly used for type II DM treatment, have a positive effect on both diabetes and neurodegeneration occurring in WS." (PMID 39064493, 2024). "GLP-1 receptor (GLP-1R) agonists and DPP-4 inhibitors are two examples of novel diabetes medications that work to enhance the function of incretins because of their critical role in glycemia regulation." (PMID 38337597, 2024). "Use of sodium-glucose cotransporter-2 (SGLT2) inhibitors (13.2% versus 43.2%), glucagon-like peptide-1 receptor agonists (GLP1-RAs) (1.0% versus 6.2%), and insulin (27.7% versus 58.1%) were lower in General medicine than in Diabetes specialist clinics." (PMID 38166049, 2024). "In the realm of clinical diabetes management, GLP‐1R antagonists and DPP‐4 inhibitors are prescribed medications aimed at stimulating the GLP‐1R signalling pathway." (PMID 38926763, 2024). "In pursuing more effective therapies for obesity and diabetes, CCK analog NN9056 has emerged as a promising candidate, especially when combined with the GLP-1R agonist semaglutide." (PMID 39529694, 2024). "In this regard, GLP-1R agonists and GLP-1 analogs (exenatide, liraglutide, and lixisenatide), used to treat diabetes, have been identified as promising drugs for PD, showing neuroprotective and neurorestorative properties." (PMID 39408276, 2024). "Glucagon-like peptide-1 receptor agonists (GLP-1RAs), such as semaglutide, are promising therapies for diabetes and obesity due to their appetite-suppressing effects and weight loss." (PMID 39027638, 2024). "However, the effect of diabetes on salivary gland GLP-1R remains unclear." (PMID 39479116, 2024). "Recently, it has been shown that semaglutide, a glucagon-like peptide-1 receptor agonist that reduces the risk of adverse cardiovascular events in patients with diabetes, can lessen the cardiovascular risk associated with overweight and obese patients in the absence of diabetes as well." (PMID 38255832, 2024). "Efpeglenatide's superiority in signaling through the glucagon-like peptide-1 receptor (GLP-1R) and its reduced desensitization compared to other GLP-1RAs is a promising development in the field of diabetes treatment." (PMID 37885518, 2023). "Glucagon-like peptide-1 receptor (GLP-1R) agonists: GLP-1R agonists, commonly used in managing diabetes, have shown neuroprotective effects in preclinical and early clinical studies." (PMID 37809189, 2023). "There is also an emerging body of evidence to suggest that glucagon-like peptide-1 receptor agonists (GLP-1RA) have actions to protect the function and structure of the kidney in models of diabetes." (PMID 37184672, 2023). "Nonetheless, Diabetes Poland, in the recently released guidelines, recommends the combination therapy of SGLT2 inhibitors with GLP-1-R agonists and metformin in patients with ASVCD or multiple risk factors regardless of the target HbA1C." (PMID 37623335, 2023). "Glucagon-like peptide-1 receptor (GLP-1R) agonists show efficacy in controlling blood glucose and serve as a treatment modality for diabetes mellitus." (PMID 38313844, 2023). "Glucagon-like peptide-1 receptor agonists (GLP-1RAs)—approved by FDA for obesity and diabetes—is one such intervention." (PMID 36013401, 2022). "Over the last 15 years, glucagon-like peptide-1 receptor agonists (GLP-1RA) have proven successful for the treatment of both obesity and diabetes." (PMID 36010663, 2022). "In this regard, molecules such as glucagon-like peptide 1 receptor agonists (GLP-1 RAs), dipeptidyl peptidase-4 inhibitors (DPP-4Is), and sodium-glucose co-transporter 2 inhibitors (SGLT-2Is), commonly used for diabetes treatment, showed promising results." (PMID 34279451, 2021).
diabetes (continued). "More prolonged studies, including those in models of diabetes are required to investigate the long-term consequences of such prolonged exposure to GCGR and GLP-1R activation by OX-SR, but the peptide does represent a potential once-weekly OXM formulation." (PMID 34093449, 2021). "Drugs in the class of the glucagon-like peptide-1 receptor agonists (GLP1Ra) have demonstrated benefits for heart function and reduced the incidence of MACE in patients with diabetes." (PMID 34445425, 2021). "SGLT2 inhibitors and glucagon-like peptide-1 receptor agonists, which have been known to prevent CKD progression, have been reimbursable for patients with diabetes in Korea since 2014 and 2015, respectively." (PMID 34945244, 2021). "One class B GPCR, the glucagon-like peptide-1 receptor (GLP-1R), has been considered as an anti-diabetes drug target and there are several peptidic drugs available for the treatment of this overwhelming disease." (PMID 31709055, 2019). "Recently, new pharmacological agents, i.e. Glucagon-like peptide-1 receptor agonists (GLP-1 RAs), have played a considerable role in the treatment of diabetes mellitus." (PMID 32184883, 2019). "In contrast, a study performed on the retinas of diabetic patients with a diabetes duration over 10 years, who had received laser photocoagulation and who were in an advanced stage of PDR, observed a decrease in GLP-1R expression with respect to the controls." (PMID 31374938, 2019). "The glucagon-like peptide-1 receptor is a class B G protein coupled receptor (GPCR) that plays key roles in glucose metabolism and is a major therapeutic target for diabetes." (PMID 27917297, 2016). "It has been shown that intravitreal injections of exendin-4 (a GLP-1R agonist) prevent ERG abnormalities and morphological features related to neurodegeneration in rats with streptozotocin-induced diabetes and in Goto-Kakizaki rats." (PMID 27123463, 2016). "In Liraglutide Effect and Action in Diabetes: Evaluation of Cardiovascular Outcome Results (LEADER) clinical trial, the effects of GLP-1R agonist liraglutide will be examined for much longer periods." (PMID 26881236, 2016). "We assessed the efficacy of simultaneous agonism at the glucagon-like peptide-1 receptor (GLP-1R) and the melanocortin-4 receptor (MC4R) for the treatment of obesity and diabetes in rodents." (PMID 25652173, 2015). "Together, these actions make GLP-1R and GIPR exciting targets for the treatment not only of diabetes and obesity but also potentially of ischemic heart disease and neurodegenerative diseases, such as Alzheimer’s disease and Parkinson’s disease." (PMID 25191754, 2014). "· Hyperglycemia has been found to lower the expression of both GLP-1R and GIPR, contributing to the diminished incretin action in hyperglycaemic states and diabetes." (PMID 23110768, 2012). "Ex-4 acts as a high-affinity agonist at the GLP-1 receptor (GLP-1-R) and, as is the case for GLP-1, it is currently under investigation for use in the treatment of diabetes mellitus." (PMID 15860526, 2005). "Glucagon-like peptide-1 receptor agonists (GLP-1 RAs), originally developed for diabetes and weight management, may offer additional vascular protective benefits through anti-inflammatory, antioxidative, and matrix-stabilizing mechanisms." (PMID 42279609, 2026). "Recent research has shown that glucagon receptor agonism (in combination with glucagon-like peptide 1 receptor [GLP-1R] agonism) rather than antagonism is more promising as a therapeutic intervention of combating diabetes and other metabolic disorders." (PMID 40280422, 2025). "Large cardiovascular and renal outcome trials have demonstrated that sodium–glucose cotransporter 2 inhibitors and glucagon-like peptide-1 receptor agonists confer substantial renoprotective and cardioprotective benefits in patients with CKD and diabetes or cardiovascular disease." (PMID 41517357, 2025).
diabetes (continued). "The targeting of the Glucagon-like peptide-1 receptor (GLP-1R) for diabetes and obesity is not a novel strategy, with recent therapeutics showing efficacy in weight loss and glycaemic control." (PMID 40832355, 2025). "Central Illustration: Efficacy of glucagon-like peptide-1 receptor agonists for prevention of stroke among patients with and without diabetes: a meta-analysis with the SELECT and FLOW trails." (PMID 40165866, 2025). "Notably, glucagon-like peptide-1 receptor agonists (GLP-1RAs), used in obesity and diabetes management, have been shown to increase adiponectin levels, linking metabolic therapies to potential sepsis immunomodulation." (PMID 40652274, 2025). "Among the therapeutic options for the treatment of hyperglycemia, thiazolidinediones (TZDs) represent a significant breakthrough in the history of diabetes management, preceding the discovery of DPP-4 inhibitors, SGLT2 inhibitors, and glucagon-like peptide-1 receptor (GLP-1R) agonists." (PMID 41302503, 2025). "Glucagon-like peptide-1 receptor agonists (GLP-1RAs), initially developed for diabetes and obesity, exhibit pleiotropic effects—including anti-inflammatory, antioxidant, and neuroprotective properties—that position them as transformative candidates for ocular therapeutics." (PMID 40777992, 2025). "This contradicts the findings of previous studies among participants without diabetes, which reported a significantly higher occurrence of diarrhea in those who received GLP-1R agonists compared to the group that received placebo." (PMID 38440786, 2024). "In already diagnosed individuals, there were significant differences in sex, diabetes duration, eGFR, PCS score, the number of people with retinopathy and the number of people using glucagon-like peptide-1 receptor agonists (GLP1-RAs), insulin and other glucose-lowering drugs." (PMID 38206363, 2024). "Previously, in mice lacking GLP-1 receptor (GLP-1R), interactions between diabetes and AD have been suggested, revealing the phenotype with impaired synaptic plasticity and memory formation." (PMID 38915346, 2024). "Cardiovascular (CV) outcome trials (CVOT) with glucagon-like peptide-1 receptor agonists (GLP-1RA), and sodium-glucose cotransporter 2 inhibitors (SGLT-2i) allowed to discover the renal benefits of these anti-diabetes compounds beyond their glucose-lowering efficacy." (PMID 38472620, 2024). "This cross-sectional study investigates rates of bariatric surgery and glucagon-like peptide-1 receptor agonist prescription among adults without diabetes in 2022 to 2023." (PMID 39453660, 2024). "Studies involving obese and overweight patients, with or without diabetes, have shown that glucagon-like peptide-1 receptor agonists (GLP-1RAs) can reduce body weight and improve glucose control." (PMID 38715796, 2024). "Glucagon-like-peptide-1 receptor agonists (GLP-1 RAs) are a class of medications currently not approved for the treatment of diabetes in pregnant women." (PMID 39126516, 2024). "GLP-1R is targeted by GLP-1R agonists, which regulate diabetes and obesity." (PMID 38801466, 2024). "Although the role of glycemic control in subjects with diabetes and DES endothelization remains elusive, activation of GLP-1R may evoke endothelization beyond glycemic control." (PMID 38066597, 2023). "Currently, except for LIR and SMG, the numbers of related clinical studies of other GLP-1R agonists are few, especially in obese or overweight people without diabetes." (PMID 36843578, 2023). "GLP-1R agonists increase GLP-1 activity while protecting the heart from hypertension, myocardial hypertrophy, and myocardial fibrosis, suggesting that GLP-1R agonist therapy is not limited to diabetes and obesity." (PMID 37681442, 2023). "There are several treatments currently available for diabetes, including sodium-glucose cotransporter-2 (SGLT2) inhibitors, dipeptidyl peptidase-4 (DPP-4) inhibitors, biguanides, thiazolidinediones (TZDs), and glucagon-like peptide-1 receptor agonists (GLP-1RAs)." (PMID 37090383, 2023).